SIRT7 (sirtuin 7)
Diseases named in the same sentence as SIRT7 in open-access papers (continued):
Sharing a sentence is not in itself a finding about the gene and the disease.
cancer (continued). "As methylation, acetylation/butyrylation at a specific lysine residues are mutually exclusive events, SIRT7 may inherently control H3K36me through its activity ultimately influencing cancer progression at least in specific malignancies." (PMID 38383727, 2024). "We propose that targeting nucleolar SIRT7 offers promise for new anti-cancer therapies." (PMID 39036727, 2024). "Given the clear role of mTOR activation in the stimulation of ribosome biogenesis and protein synthesis, it is intriguingly to speculate that in this type of malignancy SIRT7 may sustain cancer cells growth by stimulating these functions." (PMID 38383727, 2024). "We propose that pharmacological manipulation of the SIRT7/NPM/ARF axis may be exploited for antitumor therapies in cancers with intact ARF expression." (PMID 38870055, 2024). "Furthermore, cancer cells exploit SIRT7 to adapt to stressful microenvironments, thereby increasing their growth and metabolic processes via ribosome biogenesis." (PMID 39335515, 2024). "Moreover, our results showed that SIRT7 regulates chromatin stabilization by directly binding to LAP2α protein in cancer cells." (PMID 37056924, 2023). "SIRT7 is revealed to promote the autophagy in cancer progression." (PMID 37957720, 2023). "SIRT7 is a versatile nuclear-localized NAD+-dependent deacetylase with multiple biological functions, and the dysregulation of SIRT7 expression is greatly implicated in the pathogenesis of different types of cancers." (PMID 36918544, 2023). "This paradoxical role in tumorigenesis and development may be attributed to the complex molecular mechanisms by which SIRT7 regulates different types of cancer." (PMID 37056924, 2023). "Previously, it has been shown that SIRT7 is involved in promoting cancer cell autophagy." (PMID 37957720, 2023). "SIRT7 is also shown to regulate the cell proliferation and survival in cancer progression." (PMID 37957720, 2023). "Furthermore, SIRT7 suppresses AKT activation by deacetylating FK506-binding protein (FKBP51) in cancer cells under stressed conditions." (PMID 38201252, 2023). "In light of this evidence, it is reasonable that the use of SIRT7 inhibitors, in cancer cells presenting high levels of Kglu, might exert strategic anticancer effects." (PMID 37735413, 2023). "However, the use of cancer-specific mouse models and the availability of patient survival data have unveiled both oncogenic and tumor suppressive properties of SIRT7." (PMID 38234684, 2023). "In addition, SIRT7 is reported to reduce the activity of phosphoglycerate kinase 1 (PGK1) through its deacetylation in cancer cells." (PMID 38201252, 2023). "These different effects of SIRT7 on different tissues may be due to the wide range of its activity and to the dissimilar molecular profiles of the studied cancers." (PMID 35745656, 2022).
cancer (continued). "However, post-mortem gross and microscopic examinations revealed that the incidence of malignant neoplasms was similar between male WT (11 out of 22 mice, 50%) and Sirt7 KO mice (12 out of 21 mice, 57.1%)." (PMID 36429037, 2022). "Previous reports have suggested that overexpression of sirtuins in vivo may have detrimental effects, for example SIRT1 and SIRT7 overexpression is reported to be an indicator of poor prognosis in some cancers." (PMID 36561039, 2022). "However, abolishment of SIRT7 function can reverse the transformed phenotype of cancer cells and reduce their metastasis in vivo." (PMID 35422493, 2022). "SIRT7 was upregulated in multiple cancers including DTC and could promote the tumorigenesis of DTC cells in vitro and in vivo." (PMID 35136826, 2022). "In addition, in this cancer TDO2 helps to recruit SIRT7 in the chromatin after DNA damage by chemotherapeutic agents, which transiently decreases histone H3K18 acetylation and increases damage signaling and repair." (PMID 35585284, 2022). "SIRT7 is also considered an attractive target for anti-cancer therapy." (PMID 35836951, 2022). "A deeper understanding of SIRT7 function in genome stability at the molecular and physiologic levels may enable us to develop novel cancer- or ageing-related therapeutic targets." (PMID 34129782, 2021). "We pay particular attention to the implications of SIRT7 function in cancer and ageing." (PMID 34129782, 2021). "The identification of SIRT7 inhibitors could thus be of great importance with respect to cancer treatment." (PMID 34129782, 2021). "H3K18 deacetylation by SIRT7 is important for maintaining the fundamental properties of the cancer cell phenotype and knockdown of SIRT7 influences cell cycle control, and impairs cancer cell transformation." (PMID 35174171, 2021). "More systematic research is necessary to delineate how SIRT7 function might change across cancer evolution and development." (PMID 34129782, 2021). "In line with many other observations, our data further proved the importance of SIRT7 in human cancer which may serve as an attractive druggable target." (PMID 35174171, 2021). "HDAC9 and SIRT7 showed widespread CNV amplification across cancer types." (PMID 34136387, 2021). "We therefore examined whether the GSK3β–SIRT7 axis is crucial for cancer cell survival under long-term GD." (PMID 34433808, 2021). "Thus, we investigated the role of SIRT7 in the mechanism by which fasting suppresses cancer lung metastasis." (PMID 34433808, 2021). "In addition, SIRT7 can also modulate DNA repair to maintain genome integrity, and sensitize cancer cells to chemotherapeutic drugs through decreasing Akt activity." (PMID 32404984, 2020). "SIRT6 and SIRT7 were up-regulated in 14 of the 15 significantly altered cancer types." (PMID 32158696, 2020). "SIRT5, SIRT6, and SIRT7 exhibited up-regulation in multiple cancer types." (PMID 32158696, 2020). "High SIRT7-expression is a predictor of poor survival in various cancers." (PMID 32214204, 2020). "Importantly, depletion of SIRT7 markedly decreases the tumorigenicity of human cancer cell xenografts in vivo." (PMID 31121824, 2019). "SIRT7 associates with chromatin where it selectively deacetylates H3K18, an emerging epigenetic biomarker of aggressive tumors and poor clinical outcome in patients with cancer." (PMID 31196136, 2019). "In addition, PCAF induces acetylation of the K1323 site of PGK1, which in turn enhances the activity of deacetylase Sirtuin 7 (SIRT7) on K1323 and promotes cancer cell proliferation." (PMID 30995792, 2019).
cancer (continued). "Although SIRT7 depletion markedly weakens the tumorigenicity caused by human cancer cell xenografts in mice, SIRT7 itself does not give rise to oncogenic transformation of primary fibroblasts." (PMID 31817470, 2019). "The roles of SIRT 6 and SIRT7 in cancer were also cellular context dependent." (PMID 31113446, 2019). "SIRT7 also coordinates several molecular processes, inter alia tRNA and rRNA synthesis, which eventually promote the increased ribosome biogenesis vital for cancer cell growth, proliferation, and invasion." (PMID 31121824, 2019). "There is presently little known about the potential role of SIRT7 in cancer metastasis." (PMID 30001742, 2018). "SIRT7 is the least well-known member of the sirtuin family, but recent efforts have identified its involvement in various cellular processes, such as ribosome biogenesis, gene expression, cellular metabolism and cancer." (PMID 30510540, 2018). "We might assume that elevated Sirt7 levels inhibit Sirt1-mediated heterochromatin formation at pericentric regions thereby contributing to global genomic instability in cancer cells." (PMID 29963979, 2018). "In contrast to these results, there is controversy regarding whether SIRT7 is truly a cancer-promoting protein." (PMID 30001742, 2018). "High SIRT7 expression is also considered a predictor of poor survival in various cancers." (PMID 30510540, 2018). "The contradictory roles of SIRT7 in cancer may be related to its multiple interactions and functions in various cellular processes." (PMID 30510540, 2018). "SIRT7 functions as an oncogene and is upregulated in many cancer types." (PMID 30217020, 2018). "Many studies have reported mechanisms of action by which SIRT7 promotes cancer-cell growth." (PMID 30510540, 2018). "Consequently, the downregulation of SIRT7 noticeably reduces tumor growth in mice models and inhibits the properties of cancer cells such as anchorage-independent growth." (PMID 29100388, 2017). "SIRT7-mediated deacetylation of SMAD4 could be utilized as a TGF-β blocker if targeted therapy is necessary in appropriate cancer patients." (PMID 28827661, 2017). "Correspondingly, SIRT7 regulation serves as an important means for modulating ribosome biogenesis and cellular proliferation during normal cell growth and in disease states, including cancer." (PMID 27500936, 2016). "SIRT7 has been shown to function as an oncogene, being upregulated in many cancer types." (PMID 26701732, 2016). "To investigate whether SIRT7 regulates thedirectional migration of cancer cells, we performed wound-healing assaysfollowing depletion of SIRT7 by RNA interference." (PMID 25923013, 2015). "We next asked whether SIRT7 depletion affects cancer cell invasiveness using twocomplementary assays." (PMID 25923013, 2015). "Together, our findings identify SIRT7 activity as a positivedeterminant of cancer metastasis, and uncover previously unappreciated crosstalk betweentwo chromatin regulators of the sirtuin family that promote the invasive and metastaticproperties of cancer cells." (PMID 25923013, 2015). "Moreover, H3K18ac is a selective substrate of SIRT7, the activity of which is necessary for maintaining oncogenic features of human cancer cells." (PMID 26442981, 2015). "Furthermore, human cancer cell xenografts that lack SIRT7 exhibit markedly reduced oncogenicity in mice." (PMID 25486244, 2014). "Deletion of SIRT7 in a xenograft model inhibits the growth of human cancer cells." (PMID 25416589, 2014). "Finally, beyond its potential involvement in the cGAS–STING axis, SIRT7 may also influence anti-cancer immunity through additional signaling cascades that regulate inflammatory processes." (PMID 41471367, 2025). "Moreover, recent evidence indicates a complex role of SIRT7 in cancer initiation and progression." (PMID 41471367, 2025).
cancer (continued). "However, no elevated cancer incidence has been observed in SIRT7-deficient mice as compared to controls under physiological conditions, suggesting that loss of SIRT7 is insufficient to initiate tumorigenesis and likely requires additional oncogenic challenges." (PMID 41471367, 2025). "Four of these enzymes—SIRT1, SIRT2, SIRT6, and SIRT7—erase histone lysine acetylation (Kac) to regulate chromatin structure and gene transcription, and they have isozyme-specific roles as epigenetic regulators of disease pathways in cancer, neurodegeneration, and cardiometabolic disorders." (PMID 39900593, 2025). "Yet, despite this accumulating evidence, the determinants that govern this dualistic behavior remain elusive—an enigma whose resolution is essential for determining whether SIRT7 can be effectively targeted as a tailored, innovative strategy for cancer therapy." (PMID 41471367, 2025). "Moreover, studies have found that SIRT7 is widely expressed in various proliferative cancers." (PMID 40165597, 2025). "By preserving chromatin architecture and genome integrity, SIRT7 protects against malignant transformation; however, once cancer is established, it can either sustain or restrain tumor growth through context-dependent signaling programs, albeit via largely unknown mechanisms." (PMID 41471367, 2025). "Thus, deregulated SIRT7 activity in cancer cells could profoundly reshape the inflammatory and immunological landscape of tumors, ultimately influencing anti-cancer immunity." (PMID 41471367, 2025). "Furthermore, SIRT7 has been shown to mediate the desuccinylation of protein arginine methyltransferase 5 (PRMT5) at K387, which has been linked to the promotion of lipid metabolism and, consequently, cancer cell proliferation, migration, and invasion." (PMID 39781339, 2025). "Future research should not only clarify the cell-type-specific functions of SIRT7 but also determine whether its modulation can be exploited to fine-tune the interplay between tumor-intrinsic programs and anti-cancer immunity, ultimately guiding the design of next-generation therapeutic strategies." (PMID 41471367, 2025). "Moreover, increasing evidence suggests that SIRT7 acts as a key transcription factor in the development and progression of several cancers by regulating epigenetics, maintaining malignant cell phenotypes, and controlling tumor‐specific growth, invasion, and metastasis." (PMID 40165597, 2025). "Besides its role in controlling metabolism and activating cytotoxic T cells, SIRT7 may also influence anti-cancer immunity by regulating additional immune subsets, particularly CD4+ T cells." (PMID 41471367, 2025). "Consequently, SIRT7 may play a crucial role in influencing epigenetic regulation of gene expression, especially in conditions of nutrient scarcity often observed in cancer cells." (PMID 38383727, 2024). "Moreover, in cancer cells, where numerous oncogenes stimulate rRNA transcription, the increased availability of rRNA may aberrantly activate SIRT7 functions." (PMID 38383727, 2024). "Consequently, SIRT7 deficiency results in diminished HAT1-mediated histone acetylation, culminating in the destabilization of chromatin at centrosomes and consequent aneuploidy that propels cancer initiation." (PMID 38383727, 2024). "Additionally, it delves into the unique features of SIRT7, discussing their potential and specific implications in tumor initiation and progression, underscoring the promising avenue of targeting SIRT7 for the development of innovative anti-cancer therapies." (PMID 38383727, 2024). "Moreover, SIRT7 could mono-ADP-ribosylate other still unknown targets to influence their functions in cancer." (PMID 38383727, 2024). "Thus, conditions of nutrient scarcity, often occurring in cancer cells, may activate the SIRT7-macroH2A1 axis in cancer cells potentially influencing cancer progression." (PMID 38383727, 2024).
cancer (continued). "SIRT7 is a potent stimulator of ribosome biogenesis, which may indicate a dual function of increased SIRT7 expression for stimulating ribosome biogenesis in cancer cells: i) neutralization of the repressive effect of ARF on ribosome biogenesis and ii) direct stimulation of ribosome biogenesis." (PMID 38870055, 2024). "Furthermore, given that specific stress conditions prevalent in cancer cells reduce SIRT7 accumulation in the nucleolus, it is conceivable that, under such circumstances, SIRT7 may specifically interact and control distinct RNAs to control tumor progression." (PMID 38383727, 2024). "However, as H3K122 succynylation is paramount in regulating transcription, SIRT7 may act as a central player in controlling gene expression in cancer through this reaction." (PMID 38383727, 2024). "Thus, through this mechanism, SIRT7 prevents cancer cells from evading immune surveillance." (PMID 38383727, 2024). "Interestingly, GSEA analysis revealed that SIRT7-dependent DEGs in these cancer types were associated with EMT pathways, suggesting that poor patient survival in these datasets results from enhanced cancer dissemination, similar of what we observed in mice." (PMID 38234684, 2023). "However, the relationship between O-GlcNAcylation and SIRT7 in cancer cells is poorly studied." (PMID 35422493, 2022). "Similarly, SIRT7 was found to counteract cancer development by the deacetylation of WDR77." (PMID 35136826, 2022). "Thus, the reduction of SIRT7 might be an important action to raise the influence of chemoradiation therapy in cancer patients." (PMID 33705642, 2021). "SIRT7 is upregulated in many cancers, including BC; however, it has been reported that in BC it may play a dual role depending on the context, suggesting that the functional importance of SIRTs may change throughout cancer progression." (PMID 34072826, 2021). "Further identification of molecular targets of SIRT7 as well as the mechanisms governing its translocation from the nucleoli might provide a starting point for the developing a new class of anti-ageing and anti-cancer drugs." (PMID 34573343, 2021). "Furthermore, SIRT7 is upregulated in the majority of cancers, including colorectal, gastric, breast, bladder, ovarian, cervical, and hepatocellular cancers." (PMID 32214204, 2020). "Therefore, it can be assumed that SIRT7 is a worthwhile target to explore for cancer therapy." (PMID 30510540, 2018). "Based on these evidences, although still very speculative, the genetic targeting by siRNA or other approaches of Sirt1, Sirt7 or other Sirts in combination with physical exercise might represent an innovative therapeutic approach potentially beneficial in cancer." (PMID 30304806, 2018). "Thus, SIRT7 has a fundamental role in maintaining cancer phenotypes." (PMID 30510540, 2018). "In addition, several sirtuins including SIRT6 and SIRT7 are found to be critical regulators for cancer cells metabolism and therefore further studies should be implemented to indicate whether the modulation of sirtuins have implications for cancer treatment." (PMID 27659520, 2017). "In addition, SIRT7 exerts its influence on cancer metabolism." (PMID 27659520, 2017). "Therefore, SIRT7 can support cancer phenotype by inhibiting expression of tumor suppressors." (PMID 28258519, 2017). "Despite clear evidence that SIRT7 inhibits the cGAS–STING pathway across multiple cellular contexts, the relevance of this process to anti-cancer immunity remains largely unexplored." (PMID 41471367, 2025). "Recent studies illustrate that desuccinylase (e.g., SIRT5 and SIRT7) and succinyltransferase (e.g., KAT2A, CPT1A, HAT1, and alpha-KGDH) expression and malfunction are strongly related to immune escape of cancer." (PMID 40865948, 2025). "Finally, SIRT7 also regulates other metabolic pathways that may influence anti-cancer immunity." (PMID 41471367, 2025).